IGHV1-58 (immunoglobulin heavy variable 1-58)
Description:
V region of the variable domain of immunoglobulin heavy chains that participates in the antigen recognition. Immunoglobulins, also known as antibodies, are membrane-bound or secreted glycoproteins produced by B lymphocytes. In the recognition phase of humoral immunity, the membrane-bound immunoglobulins serve as receptors which, upon binding of a specific antigen, trigger the clonal expansion and differentiation of B lymphocytes into immunoglobulins-secreting plasma cells. Secreted immunoglobulins mediate the effector phase of humoral immunity, which results in the elimination of bound antigens. The antigen binding site is formed by the variable domain of one heavy chain, together with that of its associated light chain. Thus, each immunoglobulin has two antigen binding sites with remarkable affinity for a particular antigen. The variable domains are assembled by a process called V-(D)-J rearrangement and can then be subjected to somatic hypermutations which, after exposure to antigen and selection, allow affinity maturation for a particular antigen.
Synonyms: IGHV158; VH
Gene: Immunoglobulin variable (V) gene on chromosome 14 (106,622,357 to 106,622,855, reverse strand). Ensembl gene ENSG00000211968.
Subcellular location: Secreted; Cell membrane
Gene Ontology:
Molecular function: antigen binding
Biological process: immunoglobulin mediated immune response
Cellular component: extracellular region; plasma membrane
Homologues: Orthologues: mouse Ighv1-55 (64% identical), mouse Ighv1-50 (63% identical), mouse Ighv1-53 (63% identical), mouse Ighv1-64 (63% identical), mouse Ighv1-74 (63% identical), mouse Ighv1-66 (62% identical), mouse Ighv1-69 (62% identical), mouse Ighv1-84 (62% identical), mouse Ighv1-56 (61% identical), mouse Ighv1-59 (61% identical), mouse Ighv1-61 (61% identical), mouse Ighv1-75 (61% identical), and 47 more. Paralogues in human: IGHV1-3 (83% identical), IGHV1-18 (78% identical), IGHV1-2 (78% identical), IGHV1-45 (78% identical), IGHV1-69 (76% identical), IGHV1-69D (76% identical), IGHV1OR15-1 (76% identical), IGHV1-46 (74% identical), IGHV1-24 (71% identical), IGHV1OR21-1 (71% identical), IGHV7-4-1 (69% identical), IGHV1OR15-9 (68% identical), and 65 more.